KCTD3 (potassium channel tetramerization domain containing 3)
Description:
Accessory subunit of potassium/sodium hyperpolarization-activated cyclic nucleotide-gated channel 3 (HCN3) up-regulating its cell-surface expression and current density without affecting its voltage dependence and kinetics.
Synonyms: NY-REN-45
Tractability: Antibody: UniProt places it where antibodies can reach, with medium confidence; its Gene Ontology location is reachable by antibodies, with medium confidence. PROTAC: ubiquitination databases record sites on it; its protein half-life has been measured.
Gene: Protein-coding gene on chromosome 1 (215,567,022 to 215,623,007, forward strand). Ensembl gene ENSG00000136636.
Subcellular location: Cell membrane
Subcellular location (Human Protein Atlas): Cytosol
Pathways (Reactome):
Signal Transduction: CDC42 GTPase cycle
Gene Ontology:
Molecular function: protein binding
Biological process: protein homooligomerization
Cellular component: plasma membrane
Genetic constraint (gnomAD): Loss-of-function variants: 20 observed, 40.52 expected, observed/expected ratio (o/e) 0.49, 90% interval 0.35 to 0.72. The upper end of that interval is the gene's LOEUF score, 0.72, which puts it in group 2 of 6, group 1 being the genes least tolerant of losing a copy. Missense variants: 468 observed, 644 expected, observed/expected ratio (o/e) 0.73, 90% interval 0.67 to 0.78. Synonymous variants: 220 observed, 229.29 expected, observed/expected ratio (o/e) 0.96, 90% interval 0.86 to 1.07.
Homologues: Orthologues: macaque KCTD3 (99% identical), chimpanzee KCTD3 (98% identical), rabbit KCTD3 (97% identical), pig KCTD3 (96% identical), mouse Kctd3 (94% identical), rat Kctd3 (94% identical), guinea pig KCTD3 (89% identical), tropical clawed frog kctd3 (82% identical), zebrafish kctd3 (75% identical), Drosophila melanogaster CG9467 (47% identical), Caenorhabditis elegans T23B12.6 (38% identical). Paralogues in human: SHKBP1 (55% identical).
Diseases named in the same sentence as KCTD3 in open-access papers:
KCTD3 is named in the same sentence as 24 diseases in open-access papers, as found by Europe PMC text mining. Sharing a sentence is not in itself a finding about the gene and the disease. The quoted sentences say what the papers report.
autism (2 papers, 2019 to 2024). Persistent deficits in social interaction and communication and interaction as well as a markedly restricted repertoire of activity and interest as well as repetitive patterns of behavior. "KCTD3 is widely expressed in the brain and has been involved in several neurocognitive and neurodevelopmental disorders, including cerebellar hypoplasia and autism." (PMID 37469193, 2024). "Varying levels of evidence support their roles in neurocognitive disorders (KCTD3), neurodevelopmental disease (KCTD7), bipolar disorder (KCTD12), autism and schizophrenia (KCTD13), movement disorders (KCTD17), cancer (KCTD11), and obesity (KCTD15)." (PMID 31197948, 2019).
developmental delay (2 papers, 2019 to 2023). "One of these genes was KCTD3, evaluated in relation to developmental delay and epilepsy." (PMID 39669245, 2023).
developmental epileptic encephalopathy (2 papers, 2023 to 2025). "A biallelic nonsense variant of the potassium channel tetramerization domain-containing protein 3 gene (KCTD3) [c.1192C>T; p.R398*] was identified in a patient with developmental epileptic encephalopathy with distinctive features and brain structural abnormalities." (PMID 37550298, 2023).
acute lymphoblastic leukemia (1 paper, 2023). Leukemia with an acute onset, characterized by the presence of lymphoblasts in the bone marrow and the peripheral blood. "Thus, among all the KCTDs examined, only two pairs of them seem to be able to discriminate not only between the ALL subtype and the relative healthy counterpart, but also between the two types of acute lymphoblastic leukemia: KCTD12 and KCTD3 for B-ALL, and KCTD1 and KCTD11 for T-ALL." (PMID 37297863, 2023).
Epileptic encephalopathy (1 paper, 2024). A condition in which epileptiform abnormalities are believed to contribute to the progressive disturbance in cerebral function. "As for Kctd3, little is known about its role in mammalian physiology, with the few reports showing its influence on milking speed in cattle, carrying over reproductive traits in pigs, and neurogenetic disorders in humans including epileptic encephalopathy." (PMID 39273066, 2024).
T-cell leukemia (1 paper, 2023). A malignant disease of the T-lymphocytes in the bone marrow, thymus, and/or blood. "KCTD3 is able to significantly discriminate between B-cell and T-cell leukemias but not between B-cell leukemias and healthy subjects." (PMID 37297863, 2023).
tumour (4 papers, 2021 to 2025). "Notably, overexpression of KCTD2 and KCTD3 in breast cancer is associated with poor prognosis and aggressive tumor phenotypes, emphasizing their possible role in promoting tumor growth and metastasis." (PMID 40832836, 2025). "Although unknown to PCa, both DST and AK8 have demonstrated tumour suppressor behaviour, conversely, KCTD3 with an unclear role in cancer." (PMID 38947031, 2024). "Interestingly, all these proteins were upregulated in IDH-wild type GBM versus non-tumour samples upon inspection of the TCGA database, with all but KCTD3 showing significant upregulation and the latter a trend." (PMID 34316702, 2021).
autosomal recessive disease (1 paper, 2023). Autosomal recessive form of disease. "With our study, we provided Moderate or Strong level of evidence for GDR for 11 genes that were not listed in OMIM as having phenotype entity: FBRSL1, AGR2, ACBD6, C1orf127, PAN2, VPS50, KCTD3, NOTCH3 (for autosomal recessive disease), FAT1, NRAP, and SCLT1." (PMID 39669245, 2023).
genetic disorders (1 paper, 2017). "WES enabled timely diagnosing of genetic diseases, validation of causality of specific genetic disorders of PTPN23, KCTD3, SCN3A, PPOX, FRMPD4, and SCN1B, and setting dual diagnoses by detecting two causative variants in distinct genes in the same patient." (PMID 27848944, 2017).
nervous system tumor (1 paper, 2021). "Furthermore, analysis of COSMIC db indicate that 4% of nervous system tumor samples present KCTD3 mutations, suggesting the need to verify KCTD3 role in this context." (PMID 34001146, 2021).
KCTD3 also shares sentences with these, for which no sentence is quoted: cancer (3 papers); epilepsy (2); schizophrenia (2); anemia (1); bipolar disorder (1); Cerebellar hypoplasia (1); channelopathies (1); Encephalopathy (1); Intellectual disability (1); microcephaly (1); movement disorder (1); neurodevelopmental disorder (1); Obesity (1); Seizure (1).